TNF (tumor necrosis factor)
Diseases named in the same sentence as TNF in open-access papers (continued):
Sharing a sentence is not in itself a finding about the gene and the disease.
tumor (continued). "Furthermore, the 1,25(OH)2D3 had direct anti-tumor effect because several oncogenes or anti-oncogenes could be regulated by vitamin D, such as TGF-β, TNF-α, p27/Kip1, c-myc, c-fos, c-jun, which were closely associated with the proliferation and differentiation of some specific cells." (PMID 28388568, 2017). "Further investigation showed that BsAb could strongly inhibit inflammatory factor production in vivo compared with control mice, including IL-6, although TNF-α was not reduced by BsAb, which may alleviate chronic inflammation during the progress of tumor treatment." (PMID 28404966, 2017). "Interestingly, FLOT1 has been reported to be crucial for coordinated assembly of signaling complexes and signal transduction induced by TNF-α, EGF, HGF and IGF-l, suggesting that FLOT1 might play an important role in mediating the heterotypic signals originate in the tumor microenvironment." (PMID 26646322, 2016). "Because treatment with TNF is associated with strong systemic toxic side effects, the cytokine TNF-related apoptosis inducing ligand (TRAIL) has evolved as the most promising alterative for cancer therapy (TRAIL induces apoptosis in tumor cells while leaving non-transformed cells mostly unaffected)." (PMID 25925126, 2015). "The observations reported here, that androgen deprivation induces TNF mRNA expression in an epithelial tumor cell line, but not the myofibroblast stromal cell line, may reflect differences inherent in tumor and tumor-associated cells as a result of the process of tumorigenesis." (PMID 26327448, 2015). "However, when we looked at potential DAMPs in 213Bi-treated MM cell supernatants, we could not detect any significant release of HMGB1, Hsp70, or TNFα or membrane expression of Hsp70, Hsp90, or calreticulin on irradiated tumor cells." (PMID 26539436, 2015). "However, the expression of cytokines, including IL-2, IFN-γ, tumor necrosis factor (TNF)-α, granulocyte-macrophage colony-stimulating factor (GM-CSF), and IL-4, and cytokine receptors such as IL-2R, IL-4R, IL-12R, and IL-15R, is up-regulated in CIK cells upon stimulation by tumor cells." (PMID 25962508, 2015). "Based on our above observation that PD-1 was upregulated on activated T cells after being exposed to tumor cells expressing ligand PD-L1, we hypothesized that the interactions of tumor cells and activated T cells could influence the production of cytokines, such as IL-2, IFN-γ, IL-10, and TNF-α." (PMID 26361042, 2015). "Considering that TNF-α could act as an autocrine and paracrine cytokine to promote the proliferation and metastasis of tumor cells, we speculated that there might be a paracrine loop between CRC cell and TAMs in the tumor microenvironment that is controlled via TNF-α." (PMID 24885636, 2014). "Importantly, abrogation of TNFα signaling does not affect the strong anti-tumor activity of IL-12." (PMID 24587231, 2014). "However, TNF-α did not affect MCA-induced tumor development." (PMID 24403255, 2013). "Importantly, the tumor cells used in this study are known to be nonmetastatic under all conditions; nevertheless, they have acquired high metastasizing abilities in vivo in mice, following a brief stimulation by TNFα + Estrogen + EGF." (PMID 24369447, 2013). "Since TNF-α has been reported to inhibit adiponectin expression, its increase could be responsible for the significant decrease in adiponectin observed in SE and EE tumor-bearing mice but not in non-tumor-bearing mice." (PMID 23272114, 2012). "However, expression of MAP17 does not inhibit TNF-induced apoptosis in Me180-sensitive tumor cells." (PMID 22973555, 2012). "However, even though TNFα induces NF-κB activation, TNFα functions primarily as a sensitizer of TRAIL-induced apoptosis and it seems that TNFα-mediated apoptosis sensitization function apparently overpowers the TNFα-induced and NF-κB-mediated tumor cell survival effects." (PMID 21264227, 2011). "However, this rise was equal in tumours perfused with or without TNF-α." (PMID 12610519, 2003).
tumor (continued). "As TNF-α by itself has no or only minimal effect on tumour growth, an increase in local concentrations of chemotherapeutic drugs might well be the main mechanism for the synergistic anti-tumour effects." (PMID 10732774, 2000). "Thus, the effect of the combined TNF-alpha and IFN-gamma therapy involved the selective destruction of the tumour vasculature, death of tumour cells and increased expression of a series of stromal cytokines, cytokine receptors and adhesion molecules, which could be implicated in the observed events." (PMID 7577463, 1995). "Mechanistically, tumor necrosis factor (TNF) from transferred cells induces dendritic cell (DC)-dependent expansion of host CD8+ T cells, conferring protection against ACT-resistant tumor cells lacking the targeted antigen." (PMID 41912536, 2026). "As for tumour Te‐EVs, small and large EVs from both HT29 and SW620 cells, but not CDD‐841‐CoN cells, significantly promoted TNF‐α and IL‐6 secretion by dTHP‐1 cells." (PMID 40326665, 2025). "This led to improved tumor clearance in murine models, with a significant increase in circulating IFN-γ, but without significant increases in IL-6 and TNF-α." (PMID 41511353, 2025). "TNFα is a critical cytokine secreted by CD8+ T cells, which not only promote apoptosis of tumor cells but also regulate the tumor microenvironment and enhance the anti-tumor response of other immune cells." (PMID 41573646, 2025). "To further determine the role of IL-4 in adaptive immune evasion, we studied cancer cell killing in co-cultures of A549 cells with tumor antigen-specific CD8+ T-cells with or without exposure to IL-4 and/or IFNγ + TNFα." (PMID 40091029, 2025). "The exosomes smoothly reached the lungs and halted tumor growth by increasing the number of CD8+ T cells and IFN-γ / TNF-α levels in the TME, with no systemic toxicity triggered." (PMID 39961904, 2025). "Conversely, the absence of TNF-α can restore low acetylation levels at K115 on IDH1, resulting in the accumulation of reductive metabolites within tumor cells." (PMID 40906076, 2025). "The presence of pro-inflammatory cytokines, such as TNF-α, IL-1, and IFN-γ, upregulates the expression of CX3CL1 on the endothelium, leading to the recruitment of non-classical monocytes to the tumor site." (PMID 41440002, 2025). "NKG2D CAR-T cells specifically recognized NKG2DL-positive ESCC cells and secreted high levels of TNF-α, IFN-γ, IL-10, and IL-2 in overnight cocultures, while no response was observed in the absence of target tumor cells." (PMID 40510363, 2025). "Specifically, we observed a significant correlation between lower tumor stages (stage 0 to IIIB) and the absence of TNF-α gene expression, suggesting its limited involvement during earlier stages of disease progression." (PMID 40869161, 2025). "Five cytokines—IFN‐γ, TNF‐α, GM‐CSF, IL‐2, and IL‐15—were detected only in the CSF of MUE cases and not in IE or neoplasia cases." (PMID 40859633, 2025). "IHC staining was performed for eight cytokine proteins—TNF-α, IFN-γ, TGF-β1, IL-1α, IL-1β, IL-2, IL-6, and IL-12—in paired PeCa tumour samples and corresponding negative-margin tissue." (PMID 41465261, 2025). "CD40, a member of the tumor necrosis factor (TNF) receptor superfamily, plays an important role not only in the immune system but also in tumor progression." (PMID 39696986, 2024). "Their findings derived from the reduction in cholesterol levels and the enhancement of tumor necrosis factor α (TNF-α)-mediated apoptosis in the absence of PCSK9, which is detrimental to tumor development." (PMID 39736777, 2024). "Stimulation of PBMC with 1B3-transfected tumor cells alone did not result in activation of CD4+ or CD8+ T cells, but CD4-CD8- T cells did show an increase in percentage IFNγ+ and TNFα+ cells suggesting that this population can respond to tumor cells directly." (PMID 39007281, 2024).
tumor (continued). "Treatment with ASTX660 + TNFα did not kill cells of the MOC1 or MEER lineage to any significant extent, leading to tumor engraftment in mice." (PMID 39458950, 2024). "Transforming growth factor-β (TGF-β) and tumor necrosis factor-α (TNF-α) are potent inducers of PAI-1 and negative modulators of the immune response to tumor cells." (PMID 38779680, 2024). "These genetic modifications facilitate NK cell migration towards OV-infected tumor cells, but do not alter their tumor-killing efficacy their production of cytokines, such as IFN-γ and TNF-α." (PMID 39066359, 2024). "This approach effectively reduces the severity of IBD without compromising the levels of TNF-α and IFN-γ, which are crucial for maintaining the efficacy of tumor immunotherapy." (PMID 39456702, 2024). "TCR135-engineered CD8+ T cells were also activated by C666-1-EBNA1 tumor cells and expressed higher levels of IFN-γ, IL-2, and TNF-α than non-transduced TCRneg-CD8 T cells." (PMID 38412034, 2024). "Unlike FasL or TNFα, TRAIL induces apoptosis in tumour cells, selectively and exhibits little to no cytotoxicity against normal human cells or murine cells." (PMID 38534365, 2024). "We found that circulating levels of CCL11, GCSF, GMCSF, MCSF, TNFα, and IL12 (p70) were higher in TKTB34-RAS tumor-bearing mice compared with control group without tumors." (PMID 38651826, 2024). "IL-2 was detectable only in presence, but not in absence, of tumor cells, while TNFα was unchanged and all other cytokines (IL-6, IFN-γ, GM-CSF, IL-10) were slightly reduced without tumor cells." (PMID 38514793, 2024). "In this study, we show that FSS has no significant impact on the secretion of TNF-α and IFN-γ in NK cells and does not enhance the sensitivity of tumor cells to the death induced by these cytokines, TRAIL, and the conditioned medium." (PMID 37575881, 2023). "On the other hand, NDV activates a non-specific anti-tumor immune response through the secretion of cytokines, including IFN-α, IFN-β, TNF-α, and IL-1, which directly activate NK cells and macrophages." (PMID 37107646, 2023). "We also obtained similar changes in the protein expression of TNF-α, IFN-γ, and IL-2 in the right non-irradiated tumor via Western blot as seen in the PCR analysis." (PMID 36835310, 2023). "This evidence implies that Ce6-PDT boosted the immune response by increasing TNF-α, IFN-γ, and IL-2 cytokine to produce systemic effects in the non-irradiated tumor." (PMID 36835310, 2023). "When compared to the control in the right non-irradiated tumor, TNF-α expression was found to increase significantly on the fourth and seventh days after PDT treatment of the left tumor." (PMID 36835310, 2023). "Indeed, by enhancing noncanonical NF‐κΒ signaling and TNF‐α production, IAPi have been shown to enhance T‐cell costimulation, macrophage function, NK cell function, and numerous other aspects of innate and adaptive anti‐tumor immunity, which have been previously reviewed." (PMID 37132167, 2023). "C3 significantly reduced the expression (mRNA level) of inflammatory molecules TNF-α, pro-IL-β, ICAM-1, and VCAM-1 in the tumor tissue, unlike cisplatin, which significantly reduced the expression of pro-IL-β and ICAM-1." (PMID 37569878, 2023). "In line with the cell populations, cytokine analysis revealed that combinational treatment also increased the population of tumor-infiltrating T cells producing IL-2 and IFN-γ (but not TNF-α) significantly more than anti-PD-1 blockade alone." (PMID 37651197, 2023). "The results have shown no systemic toxicity, but a vaccine-induced anti-tumor response with increased IFN-γ, TNF-α, IL-5 and IL-10 production." (PMID 37513985, 2023). "Neutralizing antibodies of TNF-α and IFN-γ did not abrogate tumor killing function of the supernatant." (PMID 37723178, 2023). "Studies show that the majority of the anti-tumor CD8+ T cells are in the exhausted state, and do not express interleukin-2 (IL-2) or tumor necrosis factor α (TNF-α)." (PMID 37415732, 2023).
tumor (continued). "The levels of anti-tumor immune-response-related factors (interferon-γ (IFN-γ), interleukin-10 (IL-10), tumor necrosis factor- α (TNF-α) and IL-2) were evaluated in patients with negative and positive expressions of INHBA." (PMID 36984496, 2023). "One often reported cytokine subfamily upstream of TNFα is IL-1α and IL-1β; of which, IL-1α, but not IL-1β, is produced during MMTV-PyMT tumor pathology." (PMID 37134077, 2023). "Multiple proinflammatory/immune recruitment (IL-1β, IL-6, IL-8, TNFα, IFNα, MIP-1β, CXCL12) and immune suppressive cytokines (IL-10) were found to be induced by tumor line-derived sEVs but not those derived from normal pancreatic cell lines." (PMID 37834100, 2023). "Within the tumor, CV8102 alone, and in combination with systemic anti-PD-1 treatment, induced similar amounts of IFN-α, IFN-β, IL-6, and TNF, while anti-PD-1 antibodies alone did not induce these cytokines." (PMID 36319717, 2023). "Based on the dynamic results for these four cytokines, like TNF-α, IL-2, IL-6 and IFN-γ were secreted at higher levels in the high tumor burden group than in the low tumor burden group, but the differences were not obvious." (PMID 35013456, 2022). "The expression of inflammatory cytokines, such as TNF-α, interferon-gamma (IFN-γ), IL-1, and IL-6, which act as anti-tumor effectors, did not vary between the sensitive and resistant groups." (PMID 35965549, 2022). "Comparable doses of TNF were marginally or not at all active in the same models, suggesting that the NGR-directed targeted delivery of TNF to the tumor vasculature was necessary for the efficacy of the combined therapies." (PMID 35890309, 2022). "Regardless of tumor type, patients with values of sTIM3, IFNα, IFNγ, IL1β, IL1α, IL12p70, MIP1β, IL13, sCD28, sGITR, sPDL1, IL10 and TNFα below the median had longer overall survival (p<0.05)." (PMID 36405727, 2022). "RFA increases TIL number and CD8+/CD4+ ratio in TMERFA significantly increases the Teff/Treg ratio.RFA upregulates PD‐L1 expression in tumor cells, even for distant mock metastases without ablation.HIT enhances the expression of IFN‐γ and TNF‐α." (PMID 35908281, 2022). "ERY974 increases capecitabine-induced cytotoxicity by promoting capecitabine conversion to its active form by inducing thymidine phosphorylase expression in non-inflamed MKN45 tumour through ERY974-induced IFNγ and TNFα in T cells." (PMID 36071036, 2022). "Tumor necrosis factor (TNF), also known as TNFα, can directly kill tumor cells and has no significant cytotoxic effect on normal cells; however, a key molecule in inflammation that is a proinflammatory cytokine is TNF-α." (PMID 35860432, 2022). "Tumour specimens treated with HSA presented a significant lower % expression of Bcl-xL, TNF-α, COX2, and ESR1 and compared to the specimens in the non-treated control group." (PMID 35386216, 2022). "A lower percentage of immunopositive cells for Bcl-xL, TNF-α, and COX-2 was also observed in treated tumours compared to those in the non-treated control." (PMID 35386216, 2022). "CD4 production of IFNγ, and not TNFα or CD40L, is required for the reeducation process and tumor rejection." (PMID 35903540, 2022). "No significant tumor growth was observed in the LNT-SeNPs group (tumor size = 610 ± 223 mm3, p = 0.1905) compared to the control group, nor in the TNF-α group (tumor size = 596 ± 183 mm3, p = 0.2857)." (PMID 36678748, 2022). "Concentrations of tumor necrosis factor-α (TNFα) were not increased in the plasma of LLC and C26 tumor-bearing mice compared with the respective controls." (PMID 35210363, 2022). "Activated macrophages kill tumor cells through non-specific phagocytosis or ADCC, and also indirectly by secreting TNF, NO, and other cytotoxic factors." (PMID 36405712, 2022). "Junwei Hou showed that PD-L1 under hypoxia switched TNFα-derived-apoptosis to pyroptosis mediated by noncanonical caspase-8 in MDA-MB-231 and 4T1 cells, eventually contributes to tumor necrosis." (PMID 36119049, 2022).
tumor (continued). "Serum levels of TNF-α, IL-6, IL-8, MCP-1, VEGF-A, and IL-1ra at baseline were significantly higher in SLE patients without skin involvement than in those with skin involvement." (PMID 35715525, 2022). "(f, g) Linear correlation of proCAR oligomeric state vs. IFNγ, IL-2, TNFα, and GM-CSF cytokine production (normalized to CD28TM reference) from 24 hr co-culture with (e) MC57-HER2 and (f) antigen-negative MC57 tumor cells." (PMID 35506657, 2022). "Tumor necrosis factor (TNF)-related apoptosis-inducing ligand (TRAIL), a member of the large TNF superfamily, selectively triggers apoptosis in tumor cells, but not normal cells." (PMID 33923444, 2021). "TNFα-CSG treatment in preclinical cancer models effectively promotes intratumoral accumulation of cytotoxic T cells and suppresses tumour growth without systemic toxicity or increase in metastatic activity." (PMID 34683956, 2021). "With the capability to image tumor cell bioluminescence in vivo, the NF-κB transcriptional activation of B16F10 κB5-FLuc tumors were imaged over time with and without TNFα activation." (PMID 33652682, 2021). "BM tumor-specific T cells are functional, for example they produce IFN-γ and TNF-α, and in most cases they are not inhibited by Tregs in the organ." (PMID 34867987, 2021). "Other immune effector molecules in anti-tumor immunity, such as IFN and TNF, complement molecules and various enzymes have non-specific inhibitory or killing effects on tumor cells." (PMID 34692696, 2021). "The result is tumor endothelial anergy, the cellular non-response to pro-inflammatory stimulation (i.e. IFN-γ, TNF-α, and IL-1)." (PMID 34122412, 2021). "After IL-1β, TNF-α, and Shh treatment, tumor growth from the MT-KRAS cell lines SW1990 and Panc-1 was significantly induced compared to the control animals, whereas tumor growth from BxPC-3 cells was not stimulated." (PMID 34046348, 2021). "While i.t. injection of TNFα or IFNγ alone did not induce significant apoptosis in LLC tumours, co-treatment with TNFα and IFNγ induced whole tumour cell apoptosis to 24%." (PMID 34285232, 2021). "Nevertheless, the effector cytokine production capacity post peptide restimulation in the periphery and at the tumor site was comparable between the SCR and PGC-1α overexpression groups in terms of IFNγ, TNFα, granzyme B, and IL-2 production (data not shown)." (PMID 32055005, 2021). "Treated HCC patients without active/residual tumor cells had higher mRNA expression levels of antitumor cytokines, including IFN-γ, TNF-α, and IL-17 when compared with untreated HCC patients (p = 0.016; p = 0.041; p = 0.0146)." (PMID 34660300, 2021). "TNF‐α stabilized both PD‐L1 and CSN5 in ovarian and TNBC tumor cells without activating caspases (and EV2F)." (PMID 33587338, 2021). "The level of serum TNF-α was increased with tumor growth in tumor-bearing control mice, but in the RFA-treated group, the level of TNF-α had no obvious change after treatment." (PMID 34576115, 2021). "B7-H4, for example, is upregulated in tumor cells by immunosuppressive cytokines like TGF-β1 or IL-10, but not by inflammatory cytokines like IFN-γ or TNF-α." (PMID 33921301, 2021). "AH1-specific T cells, instead, produced IFNγ and TNFα both upon stimulation with beads and CT26, but not with F1F tumor cells." (PMID 33796916, 2021). "Through targeted adoptive transfer and in vitro studies, we identify that lack of PD-1 on ILC2s directly affects B16 tumor cell apoptosis, mediated through the cytotoxic properties of ILC2-derived TNF-α." (PMID 34531874, 2021). "Accumulating evidence suggests that DCs recruited to the tumor microenvironment often display a non-activated state, and by producing less IFN-α, TNF-α, and co-stimulating Treg cells, promote immunosuppression." (PMID 34638494, 2021). "Compared with the model control group, YPF increased the expression of IL-12, TNF-α, and IFN-γ in tumor and adjacent tissues (p < 0.05 and p < 0.01) but did not affect IL-2 level (p > 0.05)." (PMID 32351590, 2020).